ROGDI (rogdi atypical leucine zipper)
Synonyms: FLJ22386; ROGD1; RAV2; KTZS
Tractability: PROTAC: its protein half-life has been measured.
Gene: Protein-coding gene on chromosome 16 (4,796,962 to 4,802,926, reverse strand). Ensembl gene ENSG00000067836.
Subcellular location: Nucleus envelope; Presynapse; Cell projection, axon; Perikaryon; Cell projection, dendrite; Cytoplasmic vesicle, secretory vesicle, synaptic vesicle
Gene Ontology:
Molecular function: protein binding
Biological process: brain development; neurogenesis; odontogenesis of dentin-containing tooth; regulation of intracellular pH; vacuolar acidification
Cellular component: nuclear envelope; perikaryon; presynapse; RAVE complex; axon; dendrite; hippocampal mossy fiber to CA3 synapse; lysosome; synaptic vesicle
Genetic constraint (gnomAD): Loss-of-function variants: 46 observed, 35.65 expected, observed/expected ratio (o/e) 1.29, 90% interval 1.02 to 1.65. The synonymous counts are far from expectation, so gnomAD's model fits this gene poorly and the ratio says little. Missense variants: 509 observed, 328.31 expected, observed/expected ratio (o/e) 1.55, 90% interval 1.44 to 1.67. Synonymous variants: 236 observed, 139.21 expected, observed/expected ratio (o/e) 1.7, 90% interval 1.52 to 1.88.
Gene-disease validity (ClinGen):
ClinGen rates the evidence that ROGDI causes each of these diseases.
amelocerebrohypohidrotic syndrome (autosomal recessive): Definitive.
Homologues: Orthologues: macaque ROGDI (99% identical), chimpanzee ROGDI (97% identical), rat Rogdi (95% identical), mouse Rogdi (94% identical), guinea pig ROGDI (92% identical), dog ROGDI (91% identical), tropical clawed frog rogdi (79% identical), rabbit ROGDI (77% identical), zebrafish rogdi (75% identical), Drosophila melanogaster rogdi (38% identical), Caenorhabditis elegans H14A12.3 (24% identical).
Diseases named in the same sentence as ROGDI in open-access papers:
ROGDI is named in the same sentence as 19 diseases in open-access papers, as found by Europe PMC text mining. Sharing a sentence is not in itself a finding about the gene and the disease. The quoted sentences say what the papers report.
Kohlschutter-Tonz Syndrome (4 papers, 2017 to 2025). "Mutations in subunits of the mRAVE complex cause similar neurodevelopmental phenotypes, exemplified by DMXL2 mutations in Ohtahara syndrome and ROGDI mutations in Kohlschutter-Tonz Syndrome." (PMID 41509426, 2025). "Genetic testing identified a new missense mutation in the ROGDI gene; deleterious mutations of which have been associated with AI and Kohlschutter-Tönz syndrome." (PMID 37858137, 2023).
developmental delay (3 papers, 2023 to 2025). "Some genetic mutations, including ROGDI gene mutations, can result in the simultaneous occurrence of epilepsy and developmental delay." (PMID 37974187, 2023).
epilepsy (3 papers, 2017 to 2024). A brain disorder characterized by episodes of abnormally increased neuronal discharge resulting in transient episodes of sensory or motor neurological dysfunction, or psychic dysfunction. "Notably, BASSOON, which encodes the BASSOON protein and co-localizes with the ROGDI protein, has been recently identified as an epilepsy gene." (PMID 37974187, 2023). "The exact pathogenesis of epilepsy in KTS patients caused by ROGDI gene mutations remains unknown." (PMID 37974187, 2023). "Therefore, ROGDI gene mutation might affect the expression of the ROGDI protein, affect the expression of the co-located BASSOON protein, and disrupt the ROGDI-GABAergic signaling pathway, ultimately leading to epilepsy." (PMID 37974187, 2023).
Epileptic encephalopathy (1 paper, 2023). A condition in which epileptiform abnormalities are believed to contribute to the progressive disturbance in cerebral function. "Both variants in ROGDI and SLC13A5 cause epileptic encephalopathy and AI." (PMID 37228816, 2023).
Hyperammonemia (1 paper, 2025). An increased concentration of ammonia in the blood. "Our study characterizes a novel homozygous ROGDI variant (NM_024589.3:c.646-2A>G) identified in a Tunisian family case with KTS, renal tubular acidosis, and hyperammonemia." (PMID 39993789, 2025).
cancer (1 paper, 2022). A tumor composed of atypical neoplastic, often pleomorphic cells that invade other tissues. "Splice variants related to four genes (DBNDD2, DAP, ITPK1, and ROGDI) previously reported upregulated in breast/other human cancers were found downregulated in AKT1 silenced samples compared to control (siNoN)." (PMID 35892586, 2022).
ROGDI also shares sentences with these, for which no sentence is quoted: Ohtahara syndrome (2 papers); viral infection (2); amelogenesis imperfecta (1); Cognitive impairment (1); hypomyelinating leukodystrophy (1); infection (1); memory impairment (1); microcephaly (1); neurological disorders (1); PHARC syndrome (1); renal tubular acidosis (1); schizophrenia (1); spinocerebellar ataxia type 10 (1).